GCG (glucagon)
Diseases named in the same sentence as GCG in open-access papers (continued):
Sharing a sentence is not in itself a finding about the gene and the disease.
Hyperglycemia (continued). "Previous studies employed pancreatic clamp techniques, where combinations of insulin, glucose, or somatostatin are administered to control for hyperglycemia or isolate the role of glucagon in hepatic glucose production." (PMID 38814331, 2024). "Secondly, high protein intake stimulates the rise in hormones regulating glucose homeostasis, including glucagon, potentially resulting in hyperglycemia mediated by glycogenolysis and an increase in insulin resistance." (PMID 38257092, 2024). "Mechanistically, liver alanine catabolism driven by chronic glucocorticoid and glucagon signalling promotes hyperglycaemia and skeletal muscle wasting." (PMID 38725871, 2024). "This indicates that the fasting hyperglycemia observed in male Kcnk16 L114P (L/P) mice is likely a result of the observed increase in glucagon secretion under fasting conditions." (PMID 38700926, 2024). "Mechanistically, liver alanine catabolism mediated by the activation of glucagon signalling promoted hyperglycaemia and skeletal muscle atrophy." (PMID 38191505, 2024). "Compared to insulin monotherapy, patients with T1DM who received amylin analog in addition to insulin experienced a greater reduction in pre-prandial hyperglycemia and a corresponding decrease in glucagon levels." (PMID 39493778, 2024). "Long-acting medications such as liraglutide, semaglutide, dulaglutide, and exenatide long-acting release, comparatively, boost insulin secretion and decrease glucagon to control postprandial hyperglycemia." (PMID 39238749, 2024). "Consistent with pasireotide’s lower affinity for SSTR2 and higher affinity for SSTR5, hyperglycemia is attributed to reductions in insulin secretion with only mild inhibition of glucagon secretion." (PMID 38405148, 2024). "Research has shown that USP14 increases the levels and stability of 3′,5′-cyclic adenosine monophosphate response element-binding protein, enhancing the action of glucagon and hepatic glucose production, thereby promoting hyperglycemia." (PMID 38699234, 2024). "Compared to fasting state, insulin and GLP-1 secretion in presence of local postprandial hyperglycaemia suppresses glucagon release." (PMID 38579770, 2024). "Local insulin secretion in intra-islets plays a critical role in suppressing glucagon secretion during hyperglycemia." (PMID 39149119, 2024). "IL-6 has been shown to increase IR and induce fasting hyperglycemia by stimulating glucagon release." (PMID 39839274, 2024). "In the multiple dose STZ-diabetic (MDSD), daily i.p. injections of GABA(20 μmol/mouse, i.p.)for 7-days prior to STZ prevented hyperglycemia, increased serum insulin, decreased glucagon, restored β-cell mass and normalized α-cell mass." (PMID 39619323, 2024). "We tested our proposed mechanism of EphA4 agonism by WCDD301 suppressing glucagon hypersecretion and normalizing hyperglycemia with numerous control experiments." (PMID 38258903, 2024). "There was an additive effect of pramlintide and liraglutide in protecting against olanzapine-induced hyperglycemia, which was mirrored by reductions in glucagon and attenuated markers of dyslipidemia." (PMID 38188526, 2024). "Based on these observations, researchers explored suppression of glucagon secretion as a possible strategy for treating hyperglycemia in T1D." (PMID 38258903, 2024). "In patients with T2DM, glucagon levels are abnormally high during hyperglycemia, and lowering blood glucagon concentrations during hyperglycemia leads to reduced hepatic glucose output and reduced insulin requirements." (PMID 39598478, 2024). "In a type 2 diabetes model, hyperglycemia, hyperinsulinemia, and proglucagon confer an opposite effect due to decreased GLP-2 expression." (PMID 38333863, 2024). "Hyperglycemia can occur due to increased levels of stress hormones such as steroids, catecholamines, glucagon, and decreased insulin levels due to stress." (PMID 38622332, 2024).
Hyperglycemia (continued). "Benefits of this therapy for T2DM include delayed gastric emptying and, during hyperglycemia, inhibition of pancreatic α-cell glucagon production." (PMID 39720384, 2024). "Nonetheless, Alpha-2 adrenergic receptor agonists have been found to inhibit insulin release, stimulate glucagon release, or both from α and β cells, leading to hyperglycemia." (PMID 38791631, 2024). "Endogenous hormone secretion, the inflammatory response, and subsequent hyperglycemia are changed due to anesthesia and surgery (such as increases in catecholamines, cortisol, growth hormone, and glucagon)." (PMID 38414619, 2024). "It was previously reported that increased glucagon released from pancreatic α‐cells exacerbates hyperglycaemia, while high fat added to the diet had a protective effect against hyperglycaemia by producing a hypoglucagonaemic effect." (PMID 39264256, 2024). "Our group has provided strong evidence that acute olanzapine-induced hyperglycemia is mediated by increases in glucagon." (PMID 38188526, 2024). "We demonstrate here that in ZCL rats, INS-DF elevates EGP and PG levels toward those seen in ZDF rats even with GCG-DF, suggesting a dominant role of insulin resistance to cause an elevation of EGP and hyperglycemia." (PMID 38265288, 2024). "It was further noted that hepatic alanine catabolism, driven by chronic glucocorticoid and glucagon signaling, promotes hyperglycemia and skeletal muscle atrophy." (PMID 39062797, 2024). "The suppression of glucagon during hyperglycemia was more attenuated in the intermediate compared to the high tertile." (PMID 37708362, 2024). "In the glucagon tolerance test, we observed that the hepatic knockdown of CPS1 notably reduced fasting blood glucose levels and subsequently weaked the glucagon-induced hyperglycemia in mice." (PMID 39193349, 2024). "By contrast, chronic hyperglucagonemia, impaired hyperglycemia-induced suppression of glucagon and generally suppressed GH levels seem to be hallmarks of manifest T2D, thus culminating later in its development." (PMID 37708362, 2024). "Stress hormones such as glucagon and adrenaline increase hepatic glycogenolysis and gluconeogenesis, reducing muscle glucose uptake and resulting in hyperglycemia." (PMID 39101102, 2024). "The primary effect of GLP-1 is the enhancement of insulin secretion from beta-cells in response to hyperglycemia and the inhibition of glucagon release from alpha-cells." (PMID 39337658, 2024). "Our findings revealed that CPS1, a rate-limiting enzyme in the urea cycle, significantly exacerbates glucagon-induced hyperglycemia." (PMID 39193349, 2024). "Glucose elevations that are not accompanied by a parallel increase in insulin levels will result in hyperglycemia, which in turn stimulates glucagon secretion in a counter-regulatory manner." (PMID 39149119, 2024). "The ability of the α-cell to respond to hyperglycemia by suppressing glucagon secretion is also a key factor in the regulation of postprandial glucose." (PMID 39011323, 2024). "DM represents a group of physiological dysfunctions characterized by hyperglycemia due to insufficient insulin production, glucagon hypersecretion (type 1 DM), or directly from insulin resistance (type 2 DM)." (PMID 39057526, 2024). "Sensitivity analysis in which glucagon values <25 ng/mL were replaced with 25 ng/mL showed similar results (inhibition of glucagon secretion by hyperglycemia 0.85-fold [95% CI: 0.79–0.92] and by GLP-1 0.96-fold [95% CI: 0.92–0.997] in all subjects)." (PMID 38446636, 2024). "While alpha cell involvement in T1D has not been fully characterized, Unger and colleagues present evidence that glucagon hypersecretion plays a critical role in T1D hyperglycemia." (PMID 39594662, 2024). "In support of this, we have shown that acute olanzapine treatment increases circulating glucagon, whereas protection against olanzapine-induced hyperglycemia is often paralleled by reductions in glucagon and/or the glucagon:insulin ratio." (PMID 38188526, 2024).
Hyperglycemia (continued). "Further research investigating GC and glucose dynamics within acute responses and accounting for other hormones (i.e. catecholamines, insulin and glucagon), are needed to understand the relative contribution of GCs to short- versus longer-term hyperglycemia." (PMID 38949462, 2024). "Increased hepatic gluconeogenesis along with decreased glucagon levels, and decreased peripheral glucose uptake are the main mechanisms for maternal hyperglycemia induced by ACT." (PMID 38637735, 2024). "The increased glucagon release potentiates hepatic glucose production, further driving hyperglycemia and exacerbating beta-cell stress." (PMID 38612880, 2024). "Despite an ∼ 2-fold increase in active GLP1, olanzapine-induced hyperglycemia, and reductions in serum insulin were unchanged by sitagliptin, while glucagon was elevated in animals that received both drugs." (PMID 36937886, 2023). "Despite marked hyperglycaemia, impaired insulin secretion and paradoxical glucagon elevation were observed in high-fat diet-fed Gls2 CKO mice." (PMID 37147373, 2023). "The model predicts both the transient and steady-state profiles of secreted insulin and glucagon, including the typical biphasic response of normal β-cells to hyperglycemia." (PMID 37645413, 2023). "As expected, glucagon secretion from control grafts decreased in response to hyperglycemia by 30 minutes after glucose injection." (PMID 37943614, 2023). "It is known that nicotine stimulates catecholamine-mediated glucagon release from the adrenal medulla, which can increase gluconeogenesis and lead to hyperglycemia." (PMID 36987444, 2023). "TNF-α causes muscle catabolism that is also mediated by glucocorticoids, as well as by glucagon, inducing hyperglycemia and amino acid uptake by the liver." (PMID 37235434, 2023). "GLP-1 RAs exert a dual action on the endocrine pancreas cells, with a stimulation of insulin secretion by b-cells, mainly in the postprandial state, and an inhibition of glucagon secretion by a-cells, contributing to reducing hyperglycemia." (PMID 37626624, 2023). "This failure to suppress glucagon secretion significantly contributes to postprandial hyperglycemia by increasing hepatic glucose production in T2DM patients." (PMID 37764697, 2023). "Alanine is used as a precursor for gluconeogenesis and induces glucagon secretion, leading to hyperglycemia." (PMID 37029406, 2023). "Although the patient had episodes of hyperglycemia (somatostatin can inhibit both glucagon and insulin secretion), postprandial hyperinsulinemic hypoglycemia was also detected and related to postmortem findings of islet cell hyperplasia." (PMID 37371827, 2023). "Increased levels of glucagon, corticosterone, and norepinephrine in response to post-stroke hyperglycemia promotes hepatic gluconeogenesis." (PMID 36777640, 2023). "Perioperative hyperglycemia has a complicated etiology: physiologic stress increases sympathetic activation, which raises levels of glucagon, catecholamines, growth hormone, and cortisol." (PMID 36860223, 2023). "GLP1 is a hormone which can reduce the glucagon:insulin ratio and is higher in female mice, a model of protection from olanzapine-induced hyperglycemia, compared to male or ovariectomized mice." (PMID 36937886, 2023). "First, galanin promotes glucagon secretion in cultured α-cells and triggers glucagon-dependent hyperglycemia in mice." (PMID 37221172, 2023). "In fact, almost all patients with high glucagon levels (>10 pM) had normoglycemia, whereas less increased glucagon levels (<10 pM) coincided with hyperglycemia in some patients." (PMID 37492570, 2023). "The main effect of GLP-1 is the enhancement of insulin secretion from beta-cells in response to hyperglycemia and the inhibition of the release of glucagon from alpha cells." (PMID 36675217, 2023). "Normally, glucagon secretion is stimulated by a fall in blood glucose but suppressed at euglycaemia and hyperglycaemia (Göke 2008)." (PMID 37159865, 2023).
Hyperglycemia (continued). "The receptor agonists of GLP-1 (GLP-1 RAs) are able to increase the hyperglycemia-induced insulin secretion and decrease glucagon secretion, delay gastric emptying, reduce appetite and caloric intake, and they are strongly recommended in T2DM treatment." (PMID 36675217, 2023). "For hyperglycemia, glucagon was delivered by subcutaneous injections or BCD button clicks, respectively: Inj‐Glucagon (n = 4) and BCD‐Glucagon (n = 4)." (PMID 36684080, 2023). "This can lead to increased glucagon secretion and a higher glucagon-to-C-peptide ratio, further exacerbating hyperglycemia." (PMID 37409229, 2023). "In the early stages of DN, hyperglycemia causes the release of vasoactive mediators such as VEGF, NO, glucagon, insulin-like growth factor 1 (IGF-1), and prostaglandins." (PMID 37239172, 2023). "Hyperglycemia induced by glucagon was found to induce tumor growth and angiogenesis through a HIF/VEGF-associated signaling pathway." (PMID 36984785, 2023). "Over-secretion of glucagon by α-cells contributes to hyperglycemia in diabetes, and can even present during early stages of islet autoimmunity before β-cells are destroyed." (PMID 37152965, 2023). "Additional effects of GLP‐1 include stimulation of insulin secretion under conditions of hyperglycaemia, reduction in glucagon secretion, and slowing of gastric emptying." (PMID 36934408, 2023). "In this regard, when GLP-1R signalling was abrogated, hyperglycaemic excursions were observed, indicating that GLP-1R activation is essential in offsetting glucagon-induced hyperglycaemia." (PMID 37378828, 2023). "A case report showed that the suppression of extrapancreatic glucagon by octreotide long-acting repeatable improved the hyperglycemia in a TP patient with PNET." (PMID 36860372, 2023). "In patients with impaired glucose tolerance and T2DM, dysregulation of glucagon secretion leads to elevated fasting plasma glucagon concentrations, even during hyperglycemia." (PMID 37764697, 2023). "During the DH arm some participants were administered glucagon right before dinner announcement, resulting in inadequate meal bolus insulin, and subsequent hyperglycemia." (PMID 36755913, 2023). "Our group has provided evidence that increases in glucagon mediate acute olanzapine-induced hyperglycemia." (PMID 36937886, 2023). "In the meantime, STZ induced hyperglycemia suppressed the insulin mRNA expression and boosted the glucagon mRNA expression." (PMID 37520251, 2023). "Exenatide reduces fasting and postprandial hyperglycemia by increasing insulin secretion in a glucose-dependent manner, while also suppressing excess glucagon production." (PMID 37685355, 2023). "Glucagon and catecholamine are the main glucagon-regulating hormones involved in hyperglycemia response." (PMID 37735519, 2023). "On the other hand, long-acting GLP-1 agonists have shown substantial decreases in fasting blood glucose levels and modest reductions of postprandial hyperglycemia with strong stimulations of fasting insulin secretions and reductions of glucagon secretion." (PMID 35054924, 2022). "Insulin administration inhibits the glucose-sensing system in rainbow trout brains, and glucagon antagonizes insulin effects in fish, resulting in rapid and wide-ranging hyperglycemia." (PMID 36860440, 2022). "The reported hyperglycemia following the use of xylazine is probably due to a reduction in insulin release from the β-cells in the pancreas and/or an increase in glucagon release from the α-cells." (PMID 35203217, 2022). "Short-acting GLP-1 receptor agonists have demonstrated modest reductions of fasting blood glucose levels and substantial reductions of postprandial hyperglycemia by stimulating fasting insulin secretions and decreasing glucagon secretion." (PMID 35054924, 2022). "Due to hyperglycemia and reduced insulin content in TgH mice, we examined α-cell distribution and glucagon contents in HFD-fed mice at 18-week-old." (PMID 35831364, 2022).
Hyperglycemia (continued). "Our findings provide evidence that OMP expression in α-cells has a physiological role in regulating glucagon secretion, especially in hyperglycemia." (PMID 36104518, 2022). "T2DM represents the disturbance of the metabolomic homeostasis via a low insulin:glucagon ratio, with decreased insulin and increased glucagon production pushing the balance toward hyperglycemia." (PMID 36013384, 2022). "Suppression of glucagon signaling improves glycemic control and decreases hyperglycemia in people with insulin resistance." (PMID 36002172, 2022). "In December 2020 (31 months postoperatively), we noticed the recurrence of the cutaneous lesions.Admission laboratory measurements demonstrated hyperglycemia as well as elevated blood Glucagon levels." (PMID 35638031, 2022). "Based on the association between elevated glucagon and hyperglycemia in T1D28–32, we examined the correlation between glucose and glucagon." (PMID 36566274, 2022). "Monitored with a glucometer, the GRS glucagon MN patch administered hyperglycemia group showed a negligible difference in PGLs compared to the hyperglycemia control group." (PMID 35957510, 2022). "Plasma glucagon levels in diabetics are inappropriately elevated, which contributes to increased hepatic glucose production and hyperglycemia." (PMID 36394315, 2022). "Hyperglycemia can occur because of increasing levels of stress hormones e.g., catecholamines, steroids, glucagon and decreasing levels of insulin due to stress." (PMID 35586740, 2022). "Increase in glucagon levels after a single bout of exercise was previously reported in diabetic subjects with chronic hyperglycemia, suggesting that the hyperglycemic state influences the hormonal responses to exercise." (PMID 35612843, 2022). "This shows that glucagon suppression is impaired in T2D and has an impact on both fasting and postprandial glucose levels and likely exacerbates hyperglycemia in patients with T2D." (PMID 36148302, 2022). "While we still do not understand the role the transporters play in normal alpha cell function, it is clear that inhibition can improve alpha cell function and regulate glucagon secretion in response to hyperglycaemia." (PMID 35237171, 2022). "The disease is characterized as multisystemic dysfunctions attributed to hyperglycemia resulting directly from insulin resistance (IR), inadequate insulin secretion, or enormous glucagon secretion." (PMID 35454311, 2022). "Stress-induced increases in the release of glucagon, cortisol and catecholamines promote the rate of glycogenolysis and gluconeogenesis, eventually leading to hyperglycemia." (PMID 35351149, 2022). "The OMPlox/lox;GCGcre/w mice expressed basal glucagon levels similar to those in the wild-type OMPlox/lox mice but showed resistance against streptozotocin-induced hyperglycemia." (PMID 36104518, 2022). "On the other hand, the glucagon secretion (AUC-glucagon) in the AWARE group showed significant positive correlations with two-hour post-prandial hyperglycemia (r = 0.61, P < 0.05), GV indices of MAGE (r = 0.62, P < 0.05) and GRADE-hyper (r = 0.56, P < 0.02)." (PMID 35819935, 2022). "Although both studies showed a similar effect of Eriomin on GLP-1, the glucagon reduction was twofold greater in the current study, presumably due to higher baseline levels of hyperglycemia." (PMID 35796695, 2022). "Our data showed that the clearance of the gut microbiota in TAC mice lowered glucagon and blood glucose, while the transfer of these microbiomes promoted hyperglycemia in healthy individuals." (PMID 35859583, 2022). "Our results confirm that most subjects show an anti‐phasic relationship between glucagon and insulin during hyperglycemia, as previously observed in pigs and in humans after a meal." (PMID 35822422, 2022).